LGALS3 (galectin 3)
Diseases named in the same sentence as LGALS3 in open-access papers (continued):
Sharing a sentence is not in itself a finding about the gene and the disease.
COVID-19 (continued). "In this prospective cohort of COVID-19 patients, we assessed the classification performance of circulating galectin-3 levels obtained upon hospitalization on the development of a severe outcome, defined as requirement of IMV and/or death." (PMID 35115644, 2022). "In view of the lack of a treatment strategy of cancer patients infected with COVID-19 as well as the reasonable rationale of utilizing galectin-3 as a novel therapeutic target, we have investigated the role and possible regulatory mechanisms of Gal-3 in ICC." (PMID 34109213, 2021). "Of interest, COVID-19 patients also exhibit enhanced levels of the MR-regulated proinflammatory molecule Galectin-3 (Gal-3)." (PMID 34204890, 2021). "Some inflammatory biomarkers, including IL-6, IL-1, and galectin-3 (Gal-3), have been proposed as a link between COVID-19 and AD." (PMID 33673697, 2021). "The report included the observation of significantly higher plasma galectin-3 concentrations in 23 COVID-19 patients as compared to 15 healthy controls." (PMID 34439802, 2021). "The authors measured serum galectin-1, galectin-3, and prostaglandin E in the samples of 84 patients with confirmed COVID-19, treated in a tertiary hospital in Turkey, and 58 healthy controls." (PMID 34439802, 2021). "Still, serum galectin-3 predicted more severe COVID-19 independently of age and Charlson comorbidity index." (PMID 34439802, 2021). "Single cell analysis has also shown significantly elevated levels of galectin 3 (Gal-3) in macrophages, monocytes, and dendritic cells in patients with severe COVID-19 as compared to mild disease." (PMID 33082935, 2020). "Hereby, we present compelling evidences on the potential role of galectin-3 in COVID-19 in the regulation of the inflammatory response, fibrosis and infection progression." (PMID 32973815, 2020). "However, more consistent findings have emerged in COVID-19 patients, where galectin-3 has been shown to be correlated with disease severity and inflammatory burden." (PMID 40733621, 2025). "Also, Galectin-3 is significant for defining the relationship between cardiac fibrosis and COVID-19." (PMID 39598149, 2024). "In addition, Galectin-3 is highly important for defining the relation between cardiac fibrosis and COVID-19." (PMID 39598149, 2024). "In COVID-19, but not in other acute respiratory diseases, galectin-3 is associated with platelet activation markers and increased thrombogenicity markers." (PMID 37175392, 2023). "Notably, galectin-3 levels are increased in serum of COVID-19 patients and correlates with COVID-19 severity." (PMID 36755799, 2023). "Taking into consideration the involvement of galectin-3 in the hyperinflammation and fibrosis stages of the COVID-19 clinical course, new therapeutic approaches useful in severe cases could be suggested." (PMID 37958814, 2023). "Galectin-3 also correlates with markers of thrombogenicity and clinical disease severity, suggesting its usefulness in assessing disease severity and hypercoagulability in COVID-19 patients." (PMID 37298569, 2023). "Altogether, these data suggest that galectin-3 could be considered a possible therapeutic target in COVID-19." (PMID 37958814, 2023). "Blocking galectin-3 could be an effective solution to relieve the cell cycle arrest of CD8+ T cells in COVID-19 patients and restore their expansion ability and cell function." (PMID 37628961, 2023). "A study of COVID-19 patients hospitalized with acute respiratory failure reported that those who experienced fatal events within a 30-day follow-up period had higher levels of galectin-3." (PMID 37568870, 2023). "Galectin-3 may be upregulated in COVID-19 cohorts (A1,2,3) but the amount found in saliva were near saturation for the GCFP assay as configured." (PMID 37064248, 2023). "Galectin-3 activates NF-κB, leading to the production of pro-inflammatory cytokines and enhancing the antiviral response, which contributes to the cytokine storm observed in severe COVID-19 cases." (PMID 37298569, 2023).
COVID-19 (continued). "Whether galectin-3 might be a useful therapeutic target in COVID-19 needs to be assessed in future studies." (PMID 37175392, 2023). "Some of the detrimental effects of increasing levels of Gal-3BP in COVID-19 patients could be due to its interaction with galectin-3." (PMID 35806317, 2022). "Thus, we aimed to investigate the potential of galectin-3 as a biomarker of severe COVID-19 outcomes." (PMID 35115644, 2022). "Galectin-3 (Gal-3) is a receptor present at the surface of different cell types, namely epithelial and inflammatory cells, which has been described as a severity marker in COVID-19." (PMID 36220879, 2022). "Recently it has been even postulated that galectin 3 inhibitors may be helpful in the treatment of COVID-19." (PMID 35742776, 2022). "Despite these limitations, this study demonstrates in a prospective cohort of COVID-19 patients at one of the largest health institutes in Mexico that measurement of galectin-3 levels upon hospital admission could be helpful in predicting disease progression." (PMID 35115644, 2022). "Mineralocorticoid receptor (MR) signaling and its downstream target Galectin-3 (Gal-3) are known to mediate cardiovascular inflammation and might be involved in the pathogenesis of COVID-19 complications." (PMID 34204890, 2021). "Therefore, galectin-3 has been suggested as a significant mediator and a potential drug target in COVID-19." (PMID 34439802, 2021). "This strengthens the hypothesis that galectin-3 may be involved in the pathomechanism of severe COVID-19." (PMID 34439802, 2021). "We did not observe significant association between serum galectin-3 and sex (p = 0.6) or age of the studied patients with COVID-19 (R = 0.18; p = 0.1)." (PMID 34439802, 2021). "It seems that serum galectin-3 concentration reflects the severity of COVID-19 course." (PMID 35053194, 2021). "Increased serum galectin-3 in severe cases in correlation with increased concentrations of IL-6 and acute phase proteins was consistent with the cytokine storm observed in severe COVID-19." (PMID 34439802, 2021). "Moreover, we provide a strong rationale of the utility of measuring plasma galectin-3 as a prognosis biomarker for COVID-19 patients and propose that inhibition of galectin-3 represents a feasible and promising new therapeutical approach." (PMID 32973815, 2020). "Since our study lacked disease-specific control groups, such as patients with T2DM alone or COVID-19 alone, we cannot determine whether the observed elevations in galectin-3 and sICAM-1 are specific to the combination of these two conditions or primarily driven by one of them." (PMID 40733621, 2025). "However, leptin was shown to induce expression of resistin and galectin-3, and thereby may contribute to higher levels of resistin and galectin-3 in the serum of COVID-19 patients." (PMID 37238973, 2023). "However, the exact involvement of galectin-3 in the pathophysiology of thrombotic disease in COVID-19 is yet unknown." (PMID 37175392, 2023). "Our study provides new insight into the benefits of galectin-3 suppression in COVID-19 patients, which could save the lives of severe/critical patients, and also improve the lung function of patients who survive severe/critical COVID-19." (PMID 37628961, 2023). "Resistin and galectin-3 may emerge as biomarkers of COVID-19 disease activity and prognosis." (PMID 37238973, 2023). "Therefore, an effective inhibitor of galectin-3 (Gal-3) could be used to treat and prevent the transmission of COVID-19." (PMID 37112643, 2023). "The non-linear relationship of galectin-3, observed in a smoothing spline, demonstrated that higher levels of this lectin were a common characteristic of patients at high-risk of progressing to a severe COVID-19 outcome." (PMID 35115644, 2022). "However, we are only aware of a single published report on serum concentrations of galectin-3 in relation to COVID-19 severity (PubMed search on 5 May 2021)." (PMID 34439802, 2021).
COVID-19 (continued). "Our findings strengthen the hypothesis that galectin-3 may be involved in severe COVID-19." (PMID 34439802, 2021). "Recent research highlights the effectiveness of galectin-3 inhibitors, like ProLectin-M and GB0139, in reducing COVID-19 severity by lowering viral load and improving symptoms, showcasing their potential in combating virus-induced inflammation and pneumonitis." (PMID 39465409, 2024). "Therefore, galectin-3 seems to establish its involvement in the prognosis of hospitalized COVID-19 patients, suggesting that it could serve as a promising biomarker in critical COVID-19." (PMID 37958814, 2023). "LGALS3 or LGALS9 bound to these receptors, and downregulated CD8+ T proliferation and cell function in severe/critical COVID-19 patients." (PMID 37628961, 2023). "Several studies provided insights on chemerin, adiponectin, leptin, resistin, and galectin-3 levels in SARS-CoV-2-infected patients, while limited information is yet available on the adipokines apelin and visfatin in COVID-19." (PMID 37238973, 2023). "Significantly higher levels of galectin-3, galectin-9, IL-1β, IL-1Ra, IL-10, IFN-α2, IL-6, IL-18, and TNF-α were observed in severe COVID-19 and active AOSD patients compared with HC (all p<0.001)." (PMID 34367188, 2021). "Immune dysregulation in periodontitis, including an increased expression of Galectin-3 and the presence of SARS-CoV-2 in periodontal pockets, may contribute to the severity of COVID-19 in affected individuals." (PMID 40647649, 2025). "Galectin-3, a member of the β-galactoside-binding lectin family, was highly expressed by epithelial cells and had a strong effect on C10 of CD8+ T cells in patients with severe/critical COVID-19." (PMID 37628961, 2023). "For instance, 29 severe COVID-19 cases displayed higher serum galectin-3 levels than 55 non-severe cases." (PMID 37238973, 2023). "We assume that previous findings of elevated Galectin-3 in patients with COVID-19 compared to healthy controls are not specific for COVID-19 but reflects a nonspecific inflammatory response." (PMID 36203596, 2022). "This novel association between galectin-3 and CRP has not been reported in viral infection, much less in COVID-19 but it suggests the utility of this molecule in detecting the inflammatory state of patients upon hospital arrival." (PMID 35115644, 2022). "The data regarding the role and mechanisms of bradykinin and galectin-3 in severe COVID-19 cases have not been fully explored." (PMID 36338343, 2022). "Indeed, COVID-19 patients who developed pneumonia, particularly those requiring ICU admission, display increased Gal-3BP levels, which are paralleled by increased galectin-3 levels." (PMID 35806317, 2022). "Galectin-3 levels discriminated well between severe and non-severe outcomes and correlated with markers of COVID-19 severity, (CRP, NLR, D-dimer, and neutrophil count)." (PMID 35115644, 2022). "The serum concentrations of sFlt-1 was significantly higher in COVID-19 patients as compared to healthy individuals; however, we did not observe significant differences in serum galectin-3 and PTX-3." (PMID 34439802, 2021). "Given that galectin-3 shares structural similarities with the spike proteins of the β-genus of coronaviridae, including SARS-CoV-2, galectin-3 inhibitors are of particular importance in the era of COVID-19." (PMID 34035807, 2021). "In the initial scientific investigation assessing the prognostic significance of Galectin-3 in acute respiratory failure induced by COVID-19 disease, it emerged as a predictor of mortality, admission to the intensive care unit, and the development of severe ARDS in COVID-19 patients." (PMID 38674175, 2024). "Furthermore, our study focused on ICU mortality, showing that COVID-19 ICU non-survivors from the two different hospitals had significantly higher galectin-3 levels compared to survivors." (PMID 37958814, 2023).
COVID-19 (continued). "Strikingly, serum galectin-3 levels were higher in COVID-19 patients compared to controls, and could discriminate non-survivors and survivors." (PMID 37238973, 2023). "The fact that this correlation with platelet and coagulation markers was not present in the COVneg group points to a role of galectin-3 in the thrombogenic processes in COVID-19, and moreover, may have less relevance in non-COVID-19 respiratory infections." (PMID 37175392, 2023). "Similarly, another study demonstrated significantly higher galectin-3 levels in patients with severe COVID-19 compared to non-severe cases or healthy individuals." (PMID 37568870, 2023). "In this cross-sectional study, plasma levels of galectin-3, galectin-9, and soluble TIM-3 (sTIM-3) were determined by ELISA in 55 COVID-19 patients (31 non-severe and 24 severe), 23 active AOSD patients, and 31 healthy controls (HC)." (PMID 34367188, 2021).
atrial fibrillation (68 papers, 2011 to 2026). A disorder characterized by an electrocardiographic finding of a supraventricular arrhythmia characterized by the replacement of consistent P waves by rapid oscillations or fibrillatory waves that vary in size, shape and timing and are accompanied by an irregular ventricular response. "Left atrial appendage morphology, blood flow velocity and plasma galectin-3 level are important factors to evaluate the risk of left atrial appendage thrombosis in patients with atrial fibrillation." (PMID 39139162, 2024). "Galectin-3 (Gal-3) is a lectin associated with fibrosis and inflammation, and increased circulating concentrations are considered a risk factor for atrial fibrillation (AF) in humans." (PMID 39272333, 2024). "In summary, elevated serum galectin-3 was related to the left atrial enlargement and increased risk of recurrence after radiofrequency catheter ablation in patients with atrial fibrillation." (PMID 35039576, 2022). "Therefore, comprehensive analysis of left atrial appendage morphology, blood flow velocity and plasma galectin-3 level is essential to understand the risk of left atrial appendage thrombosis in patients with atrial fibrillation." (PMID 39139162, 2024). "However, the majority of pertinent studies support the view that high serum galectin-3 is indeed associated with atrial fibrillation." (PMID 37513890, 2023). "It is supposed that the profibrogenic activity of galectin-3 may induce the risk of atrial fibrillation." (PMID 36363468, 2022). "Serum galectin-3 may be a prognostic biomarker for risk stratification in patients with atrial fibrillation planned catheter ablation." (PMID 35039576, 2022). "Furthermore, galectin-3 was independently associated with atrial remodeling in patients with chronic atrial fibrillation." (PMID 33801193, 2021). "In addition, investigations employing pressure-overloaded heart models revealed that stretch-induced sarcoplasmic reticulum calcium leak serves as a causal factor for atrial fibrillation, with galectin-3 inhibition exhibiting potential in mitigating doxorubicin-induced cardiac dysfunction." (PMID 39063659, 2024). "In summary, these findings demonstrate that diabetes promotes activation of the NLRP3 inflammasome–CASP1–galectin-3 axis within atrial tissue, contributing to the initiation of atrial fibrillation." (PMID 40649732, 2025). "The primary topics in this cluster include atrial fibrillation, biomarker, cardiovascular disease, chronic heart failure, congestive heart failure, plasma galectin-3, and ventricular dysfunction." (PMID 40747108, 2025). "Previous research has demonstrated that elevated galectin-3 levels are predictive of incident atrial fibrillation and correlate with the extent of atrial fibrosis." (PMID 39451549, 2024). "The functional role of circulating galectin-3 in the context of atrial fibrillation remains to be fully elucidated." (PMID 39451549, 2024). "We searched PubMed Database by the query: “(galectin-3) AND (atrial fibrillation)” which yielded a total of 117 records." (PMID 37773454, 2023). "We assessed the clinical implications of serum galectin-3 in patients who underwent catheter ablation for atrial fibrillation." (PMID 35039576, 2022). "The study also demonstrated that serum galectin-3 concentration was significantly higher in patients with persistent atrial fibrillation than in those with paroxysmal atrial fibrillation." (PMID 35053194, 2021). "Galectin-3 plasma concentration is elevated in patients with persistent atrial fibrillation, and it is useful for the prediction of atrial fibrillation recurrence after catheter ablation." (PMID 33801193, 2021). "Serum concentrations of galectin-3 were determined in a consecutive series of patients with an ejection fraction ≤40%, addressed for ablation of persistent atrial fibrillation." (PMID 30067817, 2018).